HPX (hemopexin)
Diseases named in the same sentence as HPX in open-access papers (continued):
Sharing a sentence is not in itself a finding about the gene and the disease.
amyloid (5 papers, 2018 to 2025). "Elevated plasma HPX levels were associated with increased brain amyloid deposition as measured by PET neuroimaging using 11C-PIB." (PMID 41369364, 2025). "Notably, in AD-affected brains, amyloid deposits and microhemorrhages (hemoglobin deposits) are located in close proximity, and amyloid deposition has been shown to correlate with amyloid PET imaging and plasma hemopexin concentration." (PMID 37685872, 2023). "Hemopexin (HPX) and transferrin (Tf) were detected in the serum samples from amyloid-positive mice and were also found in amyloid deposits via immunohistochemistry, but serum samples from amyloid-negative mice did not contain HPX and Tf." (PMID 29288430, 2018).
diabetes (5 papers, 2012 to 2022). "Similarly, abnormal activities of a-antitrypsin, transferrin and hemopexin are all implicated in diabetes." (PMID 35768493, 2022). "Some researchers point out that hemopexin is upregulated in plasma from type 1 diabetes mellitus patients due to the effect of glucose-induced reactive oxygen species." (PMID 32904578, 2020). "Expression of HRMs, miR-199a, miR-21, and HRMs and miR-424 and miR-210 correlated positively with HPX, fibronectin, NO, better scar formation, and tensile strength and negatively with diabetes." (PMID 30713578, 2019). "Circulating hypoxia responsive microRNAs correlated positively with HPX, fibronectin, NO, wound contraction, closure, epithelialization, scar formation, and tensile strength and negatively with diabetes." (PMID 30713578, 2019).
ovarian carcinoma (5 papers, 2010 to 2023). A malignant neoplasm originating from the surface ovarian epithelium. "Further validation of the obtained results indicated that five proteins (Serotransferrin, Amyloid A1, Hemopexin, C-reactive protein, Albumin) were differentially expressed in ovarian cancer group." (PMID 30065196, 2018). "Further glycopeptide analysis identified unusual N- and O-glycans in clusterin, fibulin and hemopexin glycopeptides, which may be important in metastasis of ovarian cancer." (PMID 28894650, 2017). "Peptides and/or phosphopeptides of common plasma proteins such as HPR, HP, HPX, and SERPINA1 showed increased observation frequency and/or precursor intensity in ovarian cancer." (PMID 30598658, 2018). "The common acute phase proteins HP, HPR, HPX, and SERPINA all showed significant increases with ovarian cancer." (PMID 30598658, 2018). "In contrast, they reported elevated levels of a number of proteins (e.g., hemopexin, histidine-rich glycoprotein, and vitronectin) that were identified in our study but did not meet our criteria for overexpression in ovarian cancer serum." (PMID 20546617, 2010).
pancreatic cancer (5 papers, 2020 to 2024). "Overall, the proteomic studies revealed the association of radixin, moesin, c14orf166, S100P and hemopexin in LN metastasis in pancreatic cancer." (PMID 39195316, 2024). "Low-density lipoprotein receptor-related protein-1 (LRP1) reportedly acts as a receptor for hemopexin, and its expression on pancreatic cancer cells was confirmed." (PMID 32663208, 2020). "Also, hemopexin promotes invasion of the pancreatic cancer cells." (PMID 34907282, 2021). "Notably, in vitro assays showed that hemopexin promotes invasion of the pancreatic cancer cells." (PMID 32663208, 2020). "Hemopexin (HPX) promotes the invasion and metastasis of pancreatic cancer and colorectal carcinoma cells." (PMID 37511481, 2023).
preeclampsia (5 papers, 2016 to 2020). Preeclampsia is a hypertensive disorder of pregnancy that is characterized by new-onset hypertension with proteinuria presenting after 20 weeks of gestation, and depending on mild or severe forms may initially present with severe headache, visual disturbances, and hyperreflexia. "HPX expression is decreased in idiopathic intracranial hypertension and preeclampsia, which are associated with symptoms such as hypertension, pitting oedema, epigastric pain and swelling." (PMID 28924246, 2017). "Hemopexin was proposed to become depleted in the early stages of pregnancy and to rise in the third trimester when the high blood pressure symptoms of preeclampsia become apparent." (PMID 31554244, 2019). "Hemopexin levels also changed in women with preeclampsia and may be related to changes in cardiac function." (PMID 31554244, 2019).
Stroke (5 papers, 2013 to 2021). Sudden impairment of blood flow to a part of the brain due to occlusion or rupture of an artery to the brain. "B2M, THBS1, and CFD were confirmed (P <0.05) as novel CHD risk markers, and B2M, IGFBP2, and IGFBP4 were confirmed as novel stroke disease risk markers, while the assay for HPX proved to be unreliable." (PMID 24373343, 2013). "Additionally, the mechanisms underlying the neuroprotective effects of HPX in stroke remain controversial." (PMID 23758755, 2013). "Suppose sLRP1 has the ability to scavenge inflammatory blood products such as heme–hemopexin from the brain after a stroke." (PMID 33498620, 2021). "Elevated HPX expression levels would attribute to a number of functionally important cytokines by immune cells activated during the process of stroke." (PMID 23758755, 2013). "The sLRP1 receptor may bind to the heme–hemopexin complex and therefore reduce the amount of bioactive heme in the brain after stroke." (PMID 33498620, 2021). "Moreover, neuroprotective mechanisms of HPX in stroke are still equivocal." (PMID 29298658, 2018). "In addition, prior work found that HPX-null mice sustained greater infarct volumes and behavioral deficits than their wild-type counterparts in a model of transient middle cerebral artery occlusion, indicating its neuroprotective role against stroke-related damage." (PMID 23758755, 2013). "Besides, the mechanisms regulated by HPX in stroke progress are still not fully elucidated, different conclusions might be drawn through different experimental procedure." (PMID 30646866, 2019).
subarachnoid hemorrhage (5 papers, 2016 to 2020). A serious neurological disorder characterized by intracranial hemorrhage into the subarachnoid space. "The same CD91–heme–hemopexin route exists in the CNS and plays an important role in heme detoxification after subarachnoid hemorrhage in adults influencing the clinical outcome." (PMID 32210955, 2020). "Once more, HPX’s role as a potential therapeutic was reinforced in a recent review on subarachnoid hemorrhage, which compared the pathophysiology in humans and rodents, and Hp is active in outcomes in patients after subarachnoid hemorrhage or after ICH." (PMID 31554244, 2019). "Hemorrhagic stroke depletes the CSF of HPX and Hp as does subarachnoid hemorrhage as heme and iron increased in the CSF." (PMID 31554244, 2019). "Hemopexin and haptoglobin concentrations were nearly negligible in the brainafter intracerebral and subarachnoid hemorrhage." (PMID 29742229, 2018). "One of the most detailed studies on the relationship between protection of human brain cells via heme clearance by the HPX and Hp systems and activation of localized inflammatory response comes from a study by Righy and coworkers on patients after either intracerebral or subarachnoid hemorrhage." (PMID 31554244, 2019). "The extent of damage by heme to the brain is beginning to be understood and several studies in mice provide evidence that HPX is protective in intracerebral hemorrhage (ICH), subarachnoid hemorrhage, and stroke." (PMID 31554244, 2019).
endometriosis (4 papers, 2014 to 2022). The growth of functional endometrial tissue in anatomic sites outside the uterine body. "Compared to normal endometrium, endometriosis samples showed elevated levels of heme-degradation-pathway-associated genes: Hmox1 (encoding HO-1), BLVR-A and BLVR-B, and hemopexin (Hx) as well as haptoglobin (Hp), a hemoglobin scavenger." (PMID 35565370, 2022). "The decrease in hemopexin can therefore lead to oxidative stress as noted in patients of endometriosis." (PMID 24900998, 2014). "Hemopexin, a heme binding protein, was found to be downregulated in peritoneal fluid of patients proven to have endometriosis." (PMID 24900998, 2014). "Interestingly, FF albumin and hemopexin, both implicated in oxidative burden mitigation, were identified as distinct proteins in women with endometriosis who conceived, compared to women with endometriosis who did not conceive." (PMID 28701210, 2017).
liver cancer (4 papers, 2017 to 2025). An epithelial or non-epithelial malignant neoplasm that arises from the liver.
lung carcinoma (4 papers, 2018 to 2022). "HPX was also decreased in serum of patients with lung cancer." (PMID 30065196, 2018). "Recently, using 2D-DIGE, we identified several proteoforms of blood plasma proteins from lung cancer patients, including proapolipoprotein, apolipoprotein AIV, clusterin, gelsolin, fibrinogen, haptoglobin, hemopexin, transferrin, and serotransferrin." (PMID 35512017, 2022).
Lupus (4 papers, 2022 to 2025). "The Renal Activity Index for Lupus (RAIL) consists of urine protein assessment of neutrophil gelatinase–associated lipocalin, kidney injury molecule-1, monocyte chemotactic protein 1, adiponectin, hemopexin, and ceruloplasmin, which non-invasively identifies lupus nephritis (LN)." (PMID 36715772, 2023). "This study aimed to demonstrate the potential of activated leukocyte cell adhesion molecule (ALCAM), hemopexin (HPX), and peroxiredoxin 6 (PRDX6) as urine biomarkers for systemic lupus erythematosus (SLE)." (PMID 38915417, 2024). "Patients with SLE and patients with lupus nephritis (LN) showed significantly elevated ALCAM, HPX, and PRDX6 levels compared with HCs." (PMID 38915417, 2024).
lupus nephritis (4 papers, 2022 to 2024). Glomerulonephritis in the context of systemic lupus erythematosus. "ALCAM, HPX, and PRDX6 showed significant diagnostic values, especially for lupus nephritis (LN), with areas under the receiver operating characteristic curve for LN was 0.850 for ALCAM (95% CI, 0.778–0.921), 0.781 for HPX (95% CI, 0.695–0.867), and 0.714 for PRDX6 (95% CI, 0.617–0.812)." (PMID 38915417, 2024). "The Renal Activity Index for Lupus Nephritis (RAIL), comprising six urinary proteins—NGAL, MCP-1, ceruloplasmin, adiponectin, hemopexin, and Kim1—serves as an ideal predictor of renal activity in LN among children." (PMID 39104393, 2024). "We now add four additional biomarkers of importance to lupus nephritis research: MCP-1, Adiponectin, Hemopexin and Ceruloplasmin." (PMID 35967565, 2022).
nephrotic syndrome (4 papers, 2016 to 2021). A collection of symptoms that include severe edema, proteinuria, and hypoalbuminemia; it is indicative of renal dysfunction. "Additional molecules including hemopexin, angiopoietin-like-4 and CD80 are associated with nephrotic syndrome and have also been shown to cause proteinuria in experimental animals but do not appear to be relevant to FSGS." (PMID 27104120, 2016).
acute kidney injury (3 papers, 2023 to 2024). Sudden and sustained deterioration of the kidney function characterized by decreased glomerular filtration rate, increased serum creatinine or oliguria. "This was associated with higher incidence of mortality and acute kidney injury (AKI) in ageing but not adult Plasmodium-infected mice, and was corroborated by an inverse correlation between heme and HPX with serological markers of AKI in P. falciparum malaria." (PMID 38307624, 2024).
anemia (3 papers, 2021 to 2025). A reduction in the number of red blood cells, the amount of hemoglobin, and/or the volume of packed red blood cells. "However, an increase in hemopexin levels, in sense, may signify some types of anemia (in particular, hemolytic anemia), as well as chronic inflammatory processes caused by the high activity of cytokines and anaphylatoxins (complement factors), and suppression of immune reactivity." (PMID 36836953, 2023).
glioma (3 papers, 2010 to 2022). A benign or malignant brain and spinal cord tumor that arises from glial cells (astrocytes, oligodendrocytes, ependymal cells). "Among them, PCOLCE2, ERP27, PSMD13, C14orf39, C16orf86, UGCG, and HPX were identified as prognostic factors for glioma for the first time." (PMID 35873494, 2022). "We hypothesized that HPX was overexpressed due to oxidative stress buildup during the progression of glioma development, as it enacts a preventive role against oxidative damage through cellular defense mechanisms." (PMID 35873494, 2022). "Benny and colleagues demonstrated the delivery of two endogenous anti-angiogenic inhibitors, hemopexin (PEX) and a fragment of platelet factor 4 (PF-4) (PF-4/CTF), in vitro and in vivo for human glioma therapy using PLGA microspheres, with glioma growth inhibition observed." (PMID 20414333, 2010).
intracerebral hemorrhage (3 papers, 2016 to 2023). A cerebrovascular disorder characterized by bleeding into one or both cerebral hemispheres including the basal ganglia and the cerebral cortex. "However, it is important to note that this conclusion is not universally applicable, especially for systemic infections caused by certain pathogens, intracerebral hemorrhage, and Hemolytic-Uremic Syndrome (HUS), where HPX concentrations are negatively correlated with disease severity." (PMID 38022615, 2023). "Consequently, it has been proposed that a combined therapy involving hemopexin and haptoglobin may be more favorable following intracerebral hemorrhage than a hemopexin supplement alone." (PMID 38022615, 2023). "In the intracerebral hemorrhage (ICH) model, the deletion of HPX aggravates brain injury and intraperitoneal treatment of hemopexin can reduce the early-stage blood–brain barrier (BBB) disruption and cell death." (PMID 35742911, 2022).
ischemic stroke (3 papers, 2013 to 2023). A stroke disorder caused by obstruction of blood flow to the brain, due to thrombotic (local blood clot formation) or embolic (due to a blood clot or other material traveling from another site) event. "A previous study has reported that genetic deletion of HPX significantly increases the severity of the brain damage from ischemic stroke, that heme–HPX protects cells and particularly neurons against both heme- and oxidative stress-induced toxicity." (PMID 23844025, 2013). "Our study provides a new insight into the potential neuroprotective role of HPX as a contributing factor of endogenous protective mechanisms against focal cerebral ischemia injury, and HPX might be developed as a potential agent for treatment of ischemic stroke." (PMID 23758755, 2013).
liver disease (3 papers, 2016 to 2022). "We have shown that the sialylated O-glycoforms of hemopexin (HPX) in serum of patients are associated with advancing fibrosis in hepatitis C-associated liver disease." (PMID 35408612, 2022). "We have therefore designed new serologic assays for monitoring of unusual glycoforms of liver secreted proteins and evaluated, for the first time, the potential of sialylated O-glycoforms of hemopexin (HPX) in serologic monitoring of liver disease." (PMID 27688741, 2016). "At this point, we do not know the mechanism responsible for the increase of S-HPX in liver disease; further studies will be needed to explore the formation and degradation of these sialylated O-glycoforms of HPX." (PMID 27688741, 2016). "Further analysis of the precursor ion peak-intensities in XIC of the LC–MS data confirmed the trend towards increased sialylation of the O-glycoforms of HPX in liver disease." (PMID 27688741, 2016). "In conclusion, we have detected, for the first time, elevation of di-sialylated O-glycoform of HPX in liver disease and established LC–MS/MS-MRM assay for its quantification in serum." (PMID 27688741, 2016). "We have therefore selected HPX as a model liver secreted glycoprotein to study changes in the detectable site-specific O-glycoforms in liver disease." (PMID 27688741, 2016). "Thus, detectable changes in fucosylation levels of several key plasma proteins including HPX, either increase or decrease as the liver disease worsens." (PMID 31554244, 2019). "These two glycoforms change substantially in liver disease with several-fold increase in the disialylated O-glycoform of HPX and simultaneous approximately 20 % decrease in the monosialylated O-glycoform of HPX." (PMID 27688741, 2016). "Thus, HPX and properdin are poised to be potential markers for co-morbidity in drug abusers who were HIV positive, indicating both liver disease and complement activation." (PMID 31554244, 2019). "While N-glycosylation of HPX is altered in liver disease, O-glycosylation of HPX was not to our knowledge examined in this context." (PMID 27688741, 2016). "Contrary to the increased occupancy of the additional O-glycosites of HPX observed in congenital disorders of glycosylation, we do not observe changes in occupancy of additional sites in liver disease but observe increased sialylation of the O-glycan attached to the N-terminal threonine (T1) of HPX." (PMID 27688741, 2016).
prostate carcinoma (3 papers, 2015 to 2025). A carcinoma that arises from epithelial cells of the prostate gland. "In prostate cancer, HPX levels are decreased in both patient plasma and tumor stroma, with low expression correlating with poor prognosis and increased tumor volume." (PMID 41008813, 2025). "In hemopexin knockout mice, the most aggressive tumor phenotype was detected supporting the view that free heme promotes tumor growth and metastasis in prostate cancer." (PMID 38201509, 2023). "An inverse correlation between the level of free heme and hemopexin was found in the blood of patients with prostate cancer." (PMID 38201509, 2023).
Arthritis (2 papers, 2019). Inflammation of a joint. "Hemopexin was one out of seven candidate proteins and changes in HPX are known to be associated with arthritis." (PMID 31554244, 2019).
asthma (2 papers, 2015 to 2025). "A plasma protein signature of α2-macroglobulin, haptoglobin, and hemopexin was shown to discriminate between asthma and COPD with 84% accuracy." (PMID 26568662, 2015).
Cognitive impairment (2 papers, 2019 to 2025). Abnormal cognition is characterized by deficits in thinking, reasoning, or remembering. "The role of HPX in binding heme and its association with cognitive impairment suggest that iron may play an important role in cognition and physiological aging." (PMID 41369364, 2025).